CCL5 (C-C motif chemokine ligand 5)
Diseases named in the same sentence as CCL5 in open-access papers (continued):
Sharing a sentence is not in itself a finding about the gene and the disease.
acute liver failure (6 papers, 2018 to 2023). Rapid deterioration of liver function causing encephalopathy and coagulopathy. "Importantly, inhibition of CCL2 and CCL5 has been reported to reduce monocyte infiltration and alleviate acute liver failure." (PMID 34877932, 2021). "TTP is upregulated in acute liver failure (ALF), and the mRNA stability of C-C motif chemokine ligand 2 (CCL2) and C-C motif chemokine ligand 5 (CCL5) is weakened by m6A modification, thus alleviating acute liver injury." (PMID 37020540, 2023). "Here, we report that TTP was upregulated in acute liver failure (ALF), resulting in decreased mRNA stabilities of CCL2 and CCL5 through promotion of N6-methyladenosine (m6A) mRNA methylation." (PMID 34877932, 2021).
alveolitis (6 papers, 2011 to 2024). "Nasal inoculation of cotton rats with a recently isolated EV-D68 strain (VANBT/1) significantly upregulated pulmonary cytokine mRNA levels (CCL2, CCL5, CXCL1, CXCL10, IL-6, IFN-β, and IFN-γ) and provided histological evidence of peribronchiolitis and alveolitis." (PMID 34887856, 2021). "To confirm these results we evaluated the sources of CCL5 from lung biopsy tissue from all stages of pulmonary sarcoidosis, those with or without alveolitis and those on or off empiric immunosuppressive therapy." (PMID 21463523, 2011). "Using immunohistochemical techniques we determined the cellular sources of CCL5 during all stages of pulmonary sarcoidosis, those with and without alveolitis, and those on or off empiric therapy." (PMID 21463523, 2011). "Interestingly, the stage of pulmonary sarcoidosis, alveolitis, and immunosuppressive therapy at the time of pulmonary sarcoidosis diagnosis did not significantly affect the levels of CCL5." (PMID 21463523, 2011). "These immunohistochemistry results explain the elevated level of CCL5 found in patients with or without alveolitis and those on or off therapy for pulmonary sarcoidosis as all the non-necrotizing lung granulomas were producing CCL5 (for example, despite therapy or no alveolitis)." (PMID 21463523, 2011).
anemia (6 papers, 2016 to 2024). A reduction in the number of red blood cells, the amount of hemoglobin, and/or the volume of packed red blood cells. "Trend analysis of IL-2, IL-5, FGF, PDGF-bb, IL-17, CCL5, IL-4, IL-13, IFN-γ, IL-7 and TGF-β1 uncovered that as the severity of anemia increased, the concentrations of these inflammatory molecules decreased." (PMID 37143662, 2023). "Other markers ranked to separate anemia from non-anemia included IL-2, IL-1 receptor antagonist (RA), IL-13, IFN-γ, RANTES (CCL5) and IP-10." (PMID 38162636, 2023).
brain tumors (6 papers, 2016 to 2025). "CAG inhibited the activity of the JAK/STAT signaling pathway in LLC brain tumor tissues, thereby downregulating the expression of neutrophil chemotaxis-associated cytokines, including CXCL3 and CCL5." (PMID 40687724, 2025). "As CCL5 is a promiscuous ligand, binding to more than one receptor, several receptors need to be blocked to inhibit CCL5 driven axis processes in brain tumors." (PMID 32545571, 2020). "We found that in addition to the chemokines secreted by engrafted stem cells, brain tumours derived from these grafts also produced high levels of CCL5 and CXCL12." (PMID 27417157, 2016). "Notably, CCL5 showed significantly higher levels in brain tumors, suggesting a unique role in GBM." (PMID 41155216, 2025). "In the brain tumors, CD169+ macrophages produced proinflammatory chemokines, such as CXCL10 and CCL5." (PMID 36266311, 2022). "To clarify the mechanism of elevated CCL5 and CXCL12 levels in brain tumour tissues, we observed the activation of NF-κB in these tissues using western blot analysis." (PMID 27417157, 2016). "Serum CCL5 and CXCL12 levels in mice with brain tumours were obviously higher than those in mice without tumour formation and were positively correlated with the malignant grades of the tumours (P < 0.05)." (PMID 27417157, 2016).
cerebral infarction (6 papers, 2014 to 2023). An ischemic condition of the brain, producing a persistent focal neurological deficit in the area of distribution of the cerebral arteries. "Furthermore, the CCL5 gene has several polymorphisms, some of which are associated with the risk of atherothrombotic cerebral infarction." (PMID 36077361, 2022). "It has been reported that symptoms are ameliorated in a CCL5 knockout mouse model of cerebral infarction." (PMID 35525921, 2022). "CD11b, CCL5 and TNFα expression levels were not significantly elevated at 24 h following cerebral infarction compared to healthy controls." (PMID 25671080, 2014).
chronic kidney disease (6 papers, 2011 to 2025). Impairment of the renal function secondary to chronic kidney damage persisting for three or more months. "On the other side, CCL5 was found to be related to chronic kidney diseases." (PMID 37510279, 2023). "The top 25 upregulated genes showed evidence of matrix protein replacement with increased collagen synthesis (Col1a1 and Col3a1) and cellular infiltration (Cxcl1, Lyzs, Ccl5, Lyz2, Lyz, C3 VCAM1 and Ear2), consistent with the histological presence of chronic kidney disease in the mice." (PMID 22970174, 2012).
cognitive decline (6 papers, 2016 to 2025). "Increased expression of CCR3 and its ligands (CCL5, CCL11, and CCL24) are also associated with cognitive decline associated with aging." (PMID 38332938, 2024).
colorectal tumors (6 papers, 2011 to 2022). "Reports showed that CCL5-armed VACV (vvDD-CCL5) enhanced immune cell infiltration into colorectal tumors in mice." (PMID 36146629, 2022). "Data showed that both tumor progress and hepatic metastasis of colorectal tumor were dramatically decreased in CCL5−/− mice treated with anti-PD-1 Ab compared with anti-PD-1-Ab-treated CCL5+/+ mice." (PMID 29991744, 2018). "We observed increased levels of CCL5 expression in colorectal tumors (6 fold, P<0.05), liver metastases (8.5 fold, P<0.05) and lung metastases (4 fold, P<0.05) compared to healthy specimens." (PMID 22205974, 2011). "Also, induction of CXCL10 and CCL5 in colorectal tumors by hyperactivated NF-κB selectively promoted the accumulation of T effector lymphocytes but reduced the T regulatory lymphocytes." (PMID 24565056, 2014). "Since CCL5 and CXCL10 secretion is enhanced in colorectal tumors with strongtype-1 T-cell activity, the frequency of T-cells should correlate with secretionof both chemokines." (PMID 25671296, 2015). "A vaccinia strain of OV (vvDD) designed to constitutively express the chemokine CCL-5 (regulated on activation, normal T cell expressed and secreted (RANTES)) was found to increase immune cell infiltration in a mouse colorectal tumour model leading to enhanced therapeutic effects." (PMID 29157300, 2017).
demyelinating disease (6 papers, 2008 to 2025). A broad group of disorders that affect the myelin sheaths that cover the neurons. "In particular, the review discusses preclinical data concerning the role of CCL5 as a modulator of central glutamatergic transmission in healthy and demyelinating disorders." (PMID 28928746, 2017). "In a previous work, the CCL5 overexpression observed starting from the early stage of demyelinating disorder was proposed to account for the altered glutamate exocytosis detected in cortical and spinal cord glutamate nerve endings of EAE mice." (PMID 28125677, 2017). "Previously, the effects of some of these chemokines such as CCL5, CCL9, and CCL2 on the development of TMEV-induced demyelinating disease were reported." (PMID 29410948, 2018). "In particular, abnormal Ccl5 expression was detected in the cerebrospinal fluid (CSF) of patients suffering from MS and in the CNS of EAE mice implicating this chemokine in the onset of the demyelinating disease(s)." (PMID 26090715, 2015).
dry eye (6 papers, 2014 to 2025). "Other genes that were prevalently expressed, and associated with the pathogenesis of dry eye, included the chemokine receptor CCR2 and the T-cell chemoattractant, CCL5." (PMID 35562919, 2022). "The tear chemokines which have been implicated in dry eye are CX3CL1, CXCL10, CCL4/MIP-1beta, CCL3/MIP-1alpha, CCL5/RANTES, CXCL9, -10, and -11." (PMID 26605353, 2014).
esophageal squamous cell carcinoma (6 papers, 2015 to 2024). Esophageal squamous cell carcinoma (ESCC) is a type of esophageal carcinoma (EC) that can affect any part of the esophagus, but is usually located in the upper or middle third. "In esophageal SCC, CXCL10 and CCL5 have been positively correlated with CD8 and Granzyme B at the mRNA level, and tissue expression of CCL5 was positively associated with post-surgical patient survival." (PMID 33925140, 2021). "However, the expression of CCL5 and CXCL10 and its impact on the migration of CD8+ T lymphocytes remain unknown in patients with esophageal squamous cell carcinoma (ESCC)." (PMID 26317795, 2015).
infertile (6 papers, 2008 to 2025). "CCL5 (also known as regulated on activation, normal T cell expressed and secreted, RANTES) is significantly increased in the SP of individuals with HIV infection, compared to uninfected men36 but reduced in SP from infertile men with high levels of anti‐sperm antibodies." (PMID 36891953, 2023).
inflammatory bowel disease (6 papers, 2017 to 2024). A spectrum of small and large bowel inflammatory diseases of unknown etiology. "CCL5 expression is increased in inflammatory bowel disease (IBD), likely pointing to a contribution by CCL5 in the progressive tissue destruction during the inflammatory processes." (PMID 29375583, 2017). "Besides, CCL5 levels were found to be elevated in damaged tissues of inflammatory bowel disease (IBD), which then induced an influx of inflammatory factors." (PMID 35702353, 2022).
intracerebral hemorrhage (6 papers, 2022 to 2025). A cerebrovascular disorder characterized by bleeding into one or both cerebral hemispheres including the basal ganglia and the cerebral cortex. "CCL5 might be the key factor in regulating ferroptosis after intracerebral hemorrhage." (PMID 40070835, 2025). "However, much remains unknown regarding CCL5/CCR1 signaling in blood–brain barrier (BBB) permeability after intracerebral hemorrhage (ICH)." (PMID 35062973, 2022). "For example, in a mouse model of intracerebral hemorrhage, CCR5 activation by intracerebroventricularly administrated CCL5 promoted neuronal cell death in the form of inflammatory proptosis, thereby leading to neurological deficits." (PMID 37090922, 2023). "CCR5 activation promotes NLRP1-dependent neuronal pyroptosis after intracerebral hemorrhage; however, our study identified a reduction of necrosis, neurodegeneration, organ degeneration, and degeneration of the brain in TBI mice treated with CCL5." (PMID 39285280, 2024).
leptospirosis (6 papers, 2016 to 2025). A contagious bacterial infection caused by spirochetes of the genus Leptospira. "The CCL5 levels seen in sera from leptospirosis patients suggest that the same mechanisms occur in humans, since CCL5 is important for regulating inflammation." (PMID 39534703, 2024). "We suggest that CCL5 could be used as a biomarker for the complementary diagnosis of the disease, since its expression was the most prominently observed in patients with leptospirosis." (PMID 39534703, 2024). "The main findings were that CCL5, CXCL5, and CXCL9 are highly expressed during leptospirosis, indicating a special role of these molecules in the immunity and pathogenesis of the disease." (PMID 39534703, 2024). "The main findings in our study were that CCL5, CXCL5, and CXCL9 are highly expressed in human leptospirosis disease." (PMID 39534703, 2024). "Furthermore, CCL5/RANTES was found increased in kidney, spleen and blood of C57BL/6J mice at 72h post-infection with 108 L. interrogans serovar Manilae in a model of lethal leptospirosis." (PMID 40445994, 2025). "Moreover, CCL5 and CXCL9 together have been correlated with CD8+ T-cell infiltration, indicating an important role in the control of leptospirosis." (PMID 39534703, 2024).
liver cirrhosis (6 papers, 2019 to 2024). "Patients with liver cirrhosis often exhibit increased levels of CCL5, along with related chemokines CCL3 and CCL4." (PMID 38338668, 2024). "As we expected, the CCL5 expression in serum of HCC patients was more obviously increased than that of liver cirrhosis patients, while it was similar to that of healthy person." (PMID 35589690, 2022). "Among them, CCL5, CXCL9, CXCL12, LCK and CD24, which are thought to participate in the immune response, were identified as the most affected genes, suggesting a disruption of the immune response in liver cirrhosis." (PMID 34434654, 2021).
nephritis (6 papers, 2006 to 2025). Inflammation of renal tissue. "Overall, our data suggest that dual regulation of MSCs by up-regulation of CCL8 and down-regulation of CCL5 might work synergistically to ameliorate nephritis." (PMID 37567910, 2023). "Consistently, our in vivo data showed that the expression levels of CCL2, CCL3, CCL4, CCL5, CCL19, and CXCL10 increased in the kidney of MRL.Faslpr mice during the development of nephritis." (PMID 37567910, 2023). "B1R blockade has also been reported to reduce renal inflammation by downregulating renal CCL2, CCL5, and CCL7 in the anti-GBM nephritis model." (PMID 30621761, 2019). "We showed that MSCs inhibited CCL5 expression by podocytes in a TGF-β1-dependent manner, which might ameliorate nephritis by reducing leukocyte migration." (PMID 37567910, 2023).
renal cell carcinoma (6 papers, 2015 to 2024). "Combined with these two analyses, CCL5 was selected as the best potential biomarker for the detection and prediction prognosis of renal cell carcinoma." (PMID 32081834, 2020). "Renal cell carcinoma, a typical immune-excluded tumor, is considered to lack the expression of some chemokines related to T cell recruitment, such as CXCL9, CXCL10, CXCL11, CXCL13, CX3CL1, CCL2, and CCL5, in its TME, but the specific mechanisms underlying this lack of chemokines remain unclear." (PMID 36397015, 2022). "Additionally, through secreting CCL5, macrophages overexpressing APOC1 aided in the spread of renal cell cancer cells." (PMID 36908705, 2023).
schistosomiasis (6 papers, 2012 to 2022). An infectious disease caused by parasitic trematodes of the genus Schistosoma that colonize human blood vessels and release eggs that can cause granulomatous reactions leading to acute (swimmer's itch or acute schistosomiasis syndrome) or chronic disease. "On the other hand, especially CCL3 and CCL5 were shown to be elevated in schistosomiasis patients with severe disease." (PMID 30619332, 2018). "Furthermore, CCL5 mediates proliferation and activation of natural killer (NK) cells, which play a role in schistosomiasis protection in elderly populations." (PMID 26945988, 2016). "However, the increased CCL5 expression after PZQ treatment suggested that it was different from other pro-fibrosis chemokines and might be necessary for the inhibition of inflammation and fibrosis in schistosomiasis as other researches supposed." (PMID 22905138, 2012).
anaphylaxis (5 papers, 2011 to 2024). An acute hypersensitivity reaction that occurs from exposure to an allergen. "The mechanism of anaphylaxis-related basophil migration appears to be selective because no significant changes were seen for lymphocytes, PMNs, or chemotactic factors that might affect other effector cells, such as eosinophils (eg, CCL5 and CCL11)." (PMID 28342911, 2017). "A recent study demonstrated an increase in CCL2 (C-C Motif Chemokine Ligand 2) levels during human anaphylaxis, with no changes demonstrated for the chemokines CCL5 and CCL11." (PMID 33317619, 2020). "In addition, the selective elevation of IL-6 and a small panel of chemokines (CCL5, CCL20, CCL22, and CXCL1) in the spleen upon oral allergen but not saline challenge suggests their key role in eliciting anaphylaxis via the oral route." (PMID 36238931, 2022). "This suggests that this is an unbiased comparison, including the confirmation that the chemokines CCL5 and CCL11, which may affect other important effector cells of allergic inflammation such as eosinophils, are not induced during anaphylaxis." (PMID 33317619, 2020).
autism (5 papers, 2020 to 2024). Persistent deficits in social interaction and communication and interaction as well as a markedly restricted repertoire of activity and interest as well as repetitive patterns of behavior. "The current study demonstrated that PPA-induced autism in rats was characterized by a significant increase in the expression of TNF-α, IL-6, IL-17, CCL-3, CCL-5, and CXCL-16 levels as a down-regulation of OPG in the brain of PPA-induced autism-like rats, compared to the control animals." (PMID 35334937, 2022).
Chagas disease (5 papers, 2012 to 2025). A parasitic infection caused by Trypanosoma cruzi. "During Trypanosoma cruzi infection, the immune system activates a robust inflammatory response, involving cytokines and chemokines like IFN-γ, TNF, IL-6, IL-1β, CCL2, and CCL5, to control parasite replication." (PMID 40936920, 2025). "Regarding chemokines, CXCL10 and CCL5 were increased in IND and CCC patients compared to CTRL, while CCL2, CXCL9 and CXCL8 were reduced in both clinical forms of Chagas disease compared to CTRL." (PMID 38390336, 2024). "CCL5 and GZMH were upregulated in Chagas disease patients, both IND-Pre and CCC-Pre versus HD." (PMID 39119291, 2024). "Our results demonstrated that Chagas disease patients had higher serum levels of CXCL9, CXCL10 and IL-1β and lower serum levels of CCL5 than non-infected subjects." (PMID 32393333, 2020).
chordoma (5 papers, 2023 to 2025). Chordomas are rare malignant tumors arising from embryonic remnants of the notochord in axial skeleton. "Chordoma-induced secretion of CCL5 has been linked to macrophage recruitment and M2 polarization, with MVC showing inhibitory effects on these processes and subsequently suppressing chordoma proliferation, migration, and invasion." (PMID 40959082, 2025). "Although there was only this one research on CCL5 in chordoma, the study clearly confirmed the secretory source of CCL5 and verified its role in the chordoma microenvironment." (PMID 38983929, 2024). "It was also confirmed that the expression of CCL5 in recurrent chordoma was significantly higher than that in the original tumor." (PMID 38983929, 2024). "The first research on CCL5 in chordoma were just published, demonstrating a critical role for CCL5 in tumor-macrophage interactions in chordoma." (PMID 38983929, 2024). "Studies of the culture media from organoids detected the secretion of CCL5 chemokine and its knockdown, and treatment with MVC (a CCL5/CCR5 inhibitor) both significantly inhibited the progression of malignant chordoma and M2 macrophage polarisation." (PMID 37681936, 2023). "The expression level of CCL5 was significantly increased in chordoma cells, and experiments confirmed that CCL5 could induce the M2 polarization of macrophages and promote the invasion and migration of chordoma cells." (PMID 38983929, 2024). "However, this represents only part of the immunologic complexity; chordoma-secreted CCL5 has also been shown to promote macrophage recruitment and polarization toward an M2, tumor-supportive phenotype, adding another layer of complexity to the tumor’s immunoresistant biology." (PMID 41228286, 2025). "Recently, it had been discovered that kinds of cytokines and chemokines, such as TGFβ, TNFα, CCL5, IL-8, IL-6 and LIF, also as important mediators of cellular interactions, had been found to be highly expressed in chordomas and play important roles in the immune microenvironment." (PMID 38983929, 2024).